OCA2 (OCA2 melanosomal transmembrane protein)
Diseases named in the same sentence as OCA2 in open-access papers (continued):
Sharing a sentence is not in itself a finding about the gene and the disease.
melanoma (continued). "OCA2 encode melanocyte antigens presented by HLA-A∗0215, for vitiligo protection is associated with reduced functional protein, and for susceptibility to vitiligo and melanoma constitute genetic opposites, perhaps modulating immune surveillance for melanoma." (PMID 26870082, 2016). "In addition, interactive effects of MC1R and OCA2 on melanoma risk were reported." (PMID 39682251, 2024). "Variants in TYR and OCA2 may play a role in amelanotic/hypomelanotic melanoma susceptibility." (PMID 32966289, 2020). "The recent discovery of a novel OCA2 gene variant for melanoma risk in a familial melanoma pedigree provides evidence for the detrimental effects of OCA2 gene mutations on pigmentation, which supports the existing GWAS data regarding the relevance of the OCA2 gene in melanoma predisposition." (PMID 26030885, 2015). "Many well-known pigmentation genes were among the 150 most upregulated genes in the intradermal melanomas: Slc45a2, Tyrp1, Tyr, Pmel, Dct, Oca2, Mlana, Slc24a4, and Mc1r." (PMID 39804140, 2025). "Eight (10%) patients were identified that carried pathogenic mutations in known melanoma predisposition genes POT1, MITF, OCA2, SLC45A2 and TYR." (PMID 39315505, 2025). "Among the genes we identified, many are known melanoma susceptibility genes including CASP8, ARNT, and OCA2 (downregulated), PARP1, SETDB1, MTAP, SLC45A2, and MC1R (upregulated), and MX2 (both up‐ and downregulated)." (PMID 38308491, 2024). "For example, genes in cluster 2 (SPIRE2, SPATA2L), 3 (OCA2, DBNDD1, FANCA, GAS8) and 4 (URAHP, DEF8, CPNE7, MC1R) underlie the associations between melanoma and pigmentation traits." (PMID 38308491, 2024). "By contrast, a later study found an association of OCA2 variations with BCC risk and also confirmed increased melanoma risk for variations in TYRP1, SLC45A2, and ASIP and increased SCC risk (squamous cell carcinoma) for TYR and ASIP." (PMID 39682251, 2024). "Invasive melanoma cells have lower pigment levels compared with non-invasive cells and Ezh2 promotes the low-pigment phenotype in vivo by suppressing Oca2, among other targets." (PMID 36906655, 2023). "In our cohort, out of 115 patients referred to genetic counseling for melanoma, 25 tested positive (21.7%) for critical mutations: CDKN2A (n = 12), MITF (n = 3), BAP1 (n = 1), MC1R (n = 3), PTEN (n = 1), TYR (n = 2), OCA2 (n = 1), and SLC45A2 (n = 2)." (PMID 37568588, 2023). "Common noncoding polymorphisms in the HERC2/OCA2 locus have previously been associated with melanoma, with both HERC2 rs12913832 and OCA2 intron haplotype region SNPs associated with eye color and melanoma." (PMID 32966289, 2020). "Only the module turquoise had a significant enrichment (p = 0.009) of genes whose homologs displayed prognostic value in melanoma, such as Oca2, Samhd1, Nlrc5, Irf1, Ifitm3, Sp100, Dram1, Rtn1, Tcaf2, Parp10, and Grin3a." (PMID 32831131, 2020). "In another recent study of Australian and Danish melanoma families, the OCA2 p.V443I frequency was increased in cases (6 carriers in 107 cases, crude allele frequency 2.8%) and the OCA2 p.N489D was detected in three cases from one pedigree (1.4%)." (PMID 32966289, 2020). "Interaction of HERC2/OCA2 rs12913832 and rs7174027 in blue eye colour, sun sensitivity and amelanotic/hypomelanotic melanoma." (PMID 32966289, 2020). "The association of HERC2/OCA2 and CKDN2A/MTAP loci with melanoma risk were confirmed in subsequent meta-analyses." (PMID 28973033, 2017). "Recent GWAS have unveiled association between SNPs or genetic variants in MC1R, TPCN2, ASIP, KITLG, SLC24A5, TYR, IRF4, OCA2/HERC2, SLC24A4, SLC45A2, TYRP1, and pigmentation as well as melanoma." (PMID 21559390, 2011). "In the present study, a cohort of patients SPMs (n = 20) and MPMs (n = 19), sex-matched, was analyzed with our custom NGS panel that included 32 genes involved in melanoma susceptibility (e.g., CDKN2A, BAP1, POT1) and skin/hair pigmentation (e.g., TYR, TYRP1, OCA2)." (PMID 33748184, 2020).
melanoma (continued). "Notably, a p.V443I homozygous Dutch patient was reported as having 3 primary melanomas, as was another individual who was biallelic for OCA2." (PMID 32966289, 2020). "Many pigmentation genes linked to melanoma in recent GWAS such as TPCN2, ASIP, KIT, NCKX5, TYR, IRF 4, OCA2 and TYRP1 have been linked to melanoma and some of them like MC1R have dual roles in pigmentation and immune responses but many other functions of these genes remain to be discovered." (PMID 23796690, 2013). "An increased angiogenic response in individuals with appropriate OCA2 genotype may allow earlier conversion of melanoma to three-dimensional growth and thus frank disease." (PMID 22615734, 2012). "In the haplotype analysis of OCA2 (rs7497270, rs1800401, rs1800407, and rs1800414) and HERC2 (rs916977, rs7170852, and rs12913832), we observed that the TCCTTTA haplotype in males was associated with a protective effect against melanoma (OR = 0.14, 95% CI = 0.02–0.96)." (PMID 40429816, 2025). "NRAS Q61L melanomas were most enriched for modules 7 (C19orf10, ARF4, KDELR2), 13 (TIMM50, ZBED3-AS1, SERPINF1), and 15 (RAP1GAP, OCA2, PAICS)." (PMID 39796775, 2025). "However, compared to combined controls (3.13% BNMS/2.04% MGRB), there was a highly significant greater occurrence of TYR+OCA2 deleterious alleles in total melanoma cases (SMMAT P = 0.008), but not AHM (SMMAT P = 0.90), nor in comparison between AHM and PM (SMMAT P = 0.095)." (PMID 32966289, 2020). "Few high penetrance genes are known in Malignant Melanoma (MM), however, the involvement of low-penetrance genes such as MC1R, OCA2, ASIP, SLC45A2 and TYR has been observed." (PMID 23537197, 2013). "Genes such as KRT14, GJA1, S100A7, S100A9, and EHF were higher in most melanomas while genes such as CITED-1, GDF15, QPRT, OCA2, c-MET and MME were more highly expressed in NHEM." (PMID 18442402, 2008). "No amelanotic/hypomelanotic melanoma cases carried an eye and skin darkening haplotype of OCA2 (including rs7174027), present in 7.1% of pigmented melanoma cases (P = 0.0005) and 9.4% controls." (PMID 32966289, 2020). "Furthermore, by using RNA-seq data from The Cancer Genome Atlas (TCGA) melanoma cohort, we found that the mRNA level of UFL1 was negatively correlated with those of well-known targets downstream from melanin biosynthesis pathway, including OCA2 and SLC45A2." (PMID 36120581, 2022).
oculocutaneous albinism type 2 (21 papers, 2009 to 2025). "Oculocutaneous albinism type 2 (OCA2) is commonly associated with variants in the OCA2 gene, which encodes a protein critical for melanosomal pH regulation and melanin biosynthesis." (PMID 40735666, 2025). "Analyzing the structure of the genomic region of chromosome 15 associated with PWS, we observed the presence of the OCA2 gene associated with type 2 oculocutaneous albinism, tyrosinase-positive." (PMID 38902749, 2024). "Genetic studies have linked OCA2 polymorphisms and mutations to the pigmentation disorders ranging from solar lentigiens (rs4778138, rs1800414) to oculocutaneous albinism type II." (PMID 39456217, 2024). "What can we learn from the distribution of the 2.7kb deletion mutation of the OCA2 gene in oculocutaneous albinism type 2 (OCA2) in Cameroon and in sub-Saharan countries?" (PMID 38390024, 2023). "Oculocutaneous albinism type II (tyrosinase positive) is caused by biallelic pathogenic variants in the OCA2 gene." (PMID 33138774, 2020). "OCA2 is causal for oculocutaneous albinism type 2, encodes a melanosomal membrane transporter and has a major role in determining skin, hair and eye color." (PMID 29771307, 2018). "Variants in the OCA2 gene cause oculocutaneous albinism type 2 (OCA2) in humans, pink-eyed dilution in mice, and similar phenotypes in corn snakes, medaka and Mexican cave tetra fish." (PMID 28973042, 2017). "Allelic variants of OCA2 define human blue-brown eye color; OCA2 also functions in melanin synthesis within melanocytes, and aberrant OCA2 alleles cause type 2 oculocutaneous albinism in humans." (PMID 21346809, 2011). "Oculocutaneous albinism type 2 (OCA2) is caused by mutations in the OCA2 gene." (PMID 36483028, 2022). "However, this is consistent with deletion of the OCA2 gene, mutations which are known to cause non-syndromic oculocutaneous albinism type 2 (MIM 203200)." (PMID 32571899, 2021). "Interestingly, in white mink skin, the highest expression was for the Oca2 gene, which is associated with oculocutaneous albinism type 2 (Oca2), a pink-eyed dilution (p) locus." (PMID 28963476, 2017). "Research has suggested that oculocutaneous albinism type 2 may be caused by mutations in the OCA2 (pink-eye dilution homolog) gene, resulting in diluted phenotypes and sequence variations in OCA2 showed additional association with eye color." (PMID 33986980, 2021). "Oculocutaneous Albinism type 2 (OCA2) is a gene of great interest because of genetic variation affecting normal pigmentation variation in humans." (PMID 32963319, 2020). "In all three cases, it was oculocutaneous albinism type 2 (OCA2) with a homozygous 2.7-kb deletion of the P gene." (PMID 32637025, 2020). "The protein coding gene HERC2 (HECT and RLD domain containing E3 ubiquitin protein ligase 2) and its neighbouring gene OCA2 (Oculocutaneous albinism type 2) on chromosome 15 (15q13.1) have both previously demonstrated association with eye, skin and hair pigmentation." (PMID 30306274, 2018).
breast carcinoma (8 papers, 2015 to 2022). "LGSN, OCA2, and HERC2 reportedly mediated resistance to breast cancers." (PMID 36292733, 2022).
Nystagmus (8 papers, 2012 to 2025). Rhythmic, involuntary oscillations of one or both eyes related to abnormality in fixation, conjugate gaze, or vestibular mechanisms. "Clinical evaluation of the families segregating either TYR or OCA2 mutations showed nystagmus, photophobia, and loss of pigmentation in the skin or hair follicles." (PMID 22734612, 2012). "Hence, for some patients their diagnosis will be revised based on their molecular result, for example one nystagmus family (25824) was found to have biallelic variants in OCA2 (OMIM #611409) causing autosomal recessive oculocutaneous albinism type II (OMIM #203200)." (PMID 32830442, 2020). "Similarly, we do not observe nystagmus or photophobia in golden monkeys nor the consistent absence of fovea development that was recently observed in a report of TYR and OCA2-linked albino rhesus." (PMID 37522525, 2023).
skin cancer (7 papers, 2019 to 2026). "Genome wide association studies (GWAS) have identified OCA2 coding and regulatory variants linked to common skin and eye color pigment variation, skin cancer susceptibility, and retinal pigment epithelium tissue metrics." (PMID 41905947, 2026). "Moreover, variants at the HERC2/OCA2 locus have been associated with pigmentation phenotypes and the risk of developing several types of skin cancer." (PMID 36980718, 2023). "BNC2, HERC2, OCA2, RALY, and TYR are pleiotropic for Category B Phenotypes (skin colour phenotypes) and Category C Phenotypes (skin cancer phenotypes)." (PMID 35907981, 2022).
Angelman syndrome (4 papers, 2021 to 2025). A neurogenetic disorder characterized by severe intellectual deficit and distinct facial dysmorphic features. "Of note, among these different forms of OCA, OCA2 is sometimes associated with Prader–Willi syndrome (PWS) or Angelman syndrome (AS) because the p gene is localized in the distal part of the PWS/AS region." (PMID 36950135, 2023). "Proband 2 was diagnosed as OCA2 with Angelman syndrome (AS) due to a typical maternal deletion of chromosome 15q11-q13 and a novel mutation, c.1514T>C (Phe505Ser), in the p gene of the paternal chromosome." (PMID 36950135, 2023). "To date, missense mutations in HERC2 have been associated with an autosomal recessive neurodevelopmental disorder with some phenotypical similarities to Angelman syndrome, and a homozygous deletion spanning HERC2 and OCA2 causing a more severe neurodevelopmental phenotype." (PMID 32571899, 2021).
cutaneous melanoma (4 papers, 2017 to 2023). A primary melanoma arising from atypical melanocytes in the skin. "Mutations in the OCA2 gene have been proven to be related to an increased risk of skin melanoma or basal cell carcinoma." (PMID 36059514, 2022).
myopia (4 papers, 2018 to 2025). "The OCA2 gene encodes the melanosomal transmembrane protein, whose variants determine iris color and have been linked to corneal and refractive astigmatism, syndromic forms of myopia, refractive error, and type 2 oculocutaneous albinism." (PMID 34127677, 2021).
nephritis (3 papers, 2013 to 2025). Inflammation of renal tissue. "The remaining 11 genes in the region encode proteins associated with neurologic disorders (APBA2, CHRFAM7A, MTMR10, FAN1), skin and eye pigmentation or development (OCA2, HERC2, TJP1, TRPM1), nephritis (ARHGAP11B, MTMR10, FAN1), and lung disease (ENTREP2, NSMCE3)." (PMID 40013929, 2025).
ocular albinism (3 papers, 2022 to 2024). Albinism affecting the eye in which pigment of the hair and skin is normal or only slightly diluted. "In this study, two rare mutations of the OCA2 gene, c.1079C > T and c.1095_1103delAGCACTGGC, were detected in the peripheral blood of a child with ocular albinism." (PMID 38926510, 2024). "Given this context, interpreting the results poses challenges due to the risk of overgeneralizing aspects that, in reality, may be more nuanced and pertain specifically to oculocutaneous albinism type 1 (OCA1) or type 2 (OCA2), ocular albinism (OA), or Hermansky-Pudlak syndrome (HPS) for example." (PMID 38281904, 2024).
Prader-Willi syndrome (3 papers, 2007 to 2025). "Further, an association of hypopigmentation in Prader Willi syndrome and Angelman disease with a deletion on 15q11 has been found, presumable caused by mutations in OCA2." (PMID 17980020, 2007).
retinal degeneration (3 papers, 2020 to 2025). Degeneration of the retina. "Upon receipt, 5xFAD stock males were also screened for Oca2 to exclude the presence of all retinal degeneration alleles that may influence our results." (PMID 40537856, 2025). "However, a major consideration omitted in studies is the importance of excluding Pde6bRD1, Pde6bRD8, Agouti, Tyr and Oca2 genes, which are associated with retinal degeneration, that may be carried in this transgenic model." (PMID 40537856, 2025). "We performed a further screening of retinal degeneration genes Pde6bRD8, Agouti, Tyr and Oca2, including Pde6bRD1 to exclude any confounding effects which could be caused by their presence." (PMID 40537856, 2025). "Oca2 is also carried in strains such as SJL/J; the (C57BL/6 × SJL) F1 strain of origin for 5xFAD mice (MMRRC Strain #034848-JAX) and is therefore another important retinal degeneration gene to avoid in studies of other retinal disorders." (PMID 40537856, 2025).
vitiligo (3 papers, 2016 to 2024). Generalized well circumscribed patches of leukoderma that are generally distributed over symmetric body locations and is due to autoimmune destruction of melanocytes. "Previous studies have shown that an elevated risk of vitiligo is associated with HERC2 variations, which have a significant impact on determining skin and iris color besides the OCA2." (PMID 37239478, 2023).
Astigmatism (2 papers, 2018 to 2021). A type of refraction error associated with abnormal curvatures on the anterior and/or posterior surface of the cornea. "With the exception of the association signal at HERC2/OCA2, the majority of the astigmatism susceptibility loci have demonstrated association with spherical equivalent-related traits in previous GWAS analyses." (PMID 30306274, 2018). "Three of these loci also demonstrated genome-wide significant association with refractive astigmatism: LINC00340, HERC2/OCA2 and NPLOC4/TSPAN10." (PMID 30306274, 2018). "The identification of 3 genes (HERC2, OCA2 and TSPAN10) associated with eye colour and astigmatism implies that certain eye colour(s) may confer susceptibility to astigmatism or that these eye colour-related genes have distinct, pleiotropic actions that lead to astigmatism." (PMID 30306274, 2018).
autism (2 papers, 2012 to 2017). Persistent deficits in social interaction and communication and interaction as well as a markedly restricted repertoire of activity and interest as well as repetitive patterns of behavior. "Cases I and II, are carriers of the same duplication on chromosome 15 [15q11.2q13.1(SNRPN,UBE3A,ATP10A,GABRB3,OCA2) x3], both have severe autism but with different levels of cognition." (PMID 28174603, 2017).
congenital nystagmus (2 papers, 2011 to 2024). Nystagmus present at birth or caused by lesions sustained in utero or at the time of birth. "Human OCA2 patients generally have varying degrees of congenital nystagmus, reduced vision acuity, refractive errors, and some degree of color vision impairment." (PMID 38396851, 2024).
schizophrenia (2 papers, 2017 to 2021). A major psychotic disorder characterized by abnormalities in the perception or expression of reality. "We applied the framework to seventeen phenotypes and found well-replicated genes such as HERC2 and OCA2 for hair and eye color, and novel genes such as ZNF773 and PCNT for schizophrenia." (PMID 34535759, 2021).
Stickler syndrome (2 papers, 2021 to 2025). Stickler syndrome is an inherited vitreoretinopathy characterized by the association of ocular signs with more or less complete forms of Pierre-Robin sequence, bone disorders, and sensorineural deafness (10% of cases). "The corresponding phenotypic disorders of the mutated POU4F3, COL11A1, OCA2 are autosomal dominant deafness type 15, Marshall syndrome (or Stickler syndrome) and eye pigment variant I, respectively." (PMID 33345266, 2021).
anxiety disorder (1 paper, 2025). A category of psychiatric disorders which are characterized by anxious feelings or fear often accompanied by physical symptoms associated with anxiety. "The TMCC1, OCA2 and ADIPOR2 genes have also been identified in a recent cross-anxiety disorder EWAS." (PMID 40281224, 2025).
Apnea (1 paper, 2024). Lack of breathing with no movement of the respiratory muscles and no exchange of air in the lungs. "Deletion outcomes vary by type (ORPHA ID: 98,793, ORPHA ID: 177,901), including type 2 genes such as SNORD116-1, SNRPN, SNORD115-1, OCA2, MAGEL2, NDN, and their role in the development of apnea." (PMID 38902749, 2024).
autoimmune thyroid disease (1 paper, 2022). Inflammatory disease of the thyroid gland due to autoimmune responses leading to lymphocytic infiltration of the gland. "The GSEA showed that RGS8, DGKI and OCA2 were enriched in thyroid hormone production and its peripheral downstream signal transduction effects, thyroxine biosynthesis, and autoimmune thyroid diseases." (PMID 36059514, 2022). "The enrichment plots of the GSEA showed that thyroid hormone production and its peripheral downstream signalling effects, thyroxine biosynthesis, and autoimmune thyroid disease were significantly enriched in RGS8, DGKI and OCA2." (PMID 36059514, 2022).